ROM1 (retinal outer segment membrane protein 1)
Description:
Plays a role in rod outer segment (ROS) morphogenesis (By similarity). May play a role with PRPH2 in the maintenance of the structure of ROS curved disks (By similarity). Plays a role in the organization of the ROS and maintenance of ROS disk diameter (By similarity). Involved in the maintenance of the retina outer nuclear layer (By similarity).
Synonyms: ROSP1; TSPAN23; ROM; RP7
Tractability: Antibody: its Gene Ontology location is reachable by antibodies, with high confidence; UniProt predicts a signal peptide or a membrane-spanning region; the Human Protein Atlas places it where antibodies can reach.
Gene: Protein-coding gene on chromosome 11 (62,611,722 to 62,615,116, forward strand). Ensembl gene ENSG00000149489.
Subcellular location: Photoreceptor inner segment membrane; Photoreceptor outer segment membrane
Subcellular location (Human Protein Atlas): Cytosol; Plasma membrane; Nucleoplasm
Gene Ontology:
Molecular function: protein binding; protein homodimerization activity
Biological process: visual perception
Cellular component: plasma membrane; membrane; photoreceptor outer segment; photoreceptor outer segment membrane
Genetic constraint (gnomAD): Loss-of-function variants: 20 observed, 28.99 expected, observed/expected ratio (o/e) 0.69, 90% interval 0.48 to 1. The upper end of that interval is the gene's LOEUF score, 1, which puts it in group 4 of 6, group 1 being the genes least tolerant of losing a copy. Missense variants: 436 observed, 459.82 expected, observed/expected ratio (o/e) 0.95, 90% interval 0.88 to 1.03. Synonymous variants: 200 observed, 215.51 expected, observed/expected ratio (o/e) 0.93, 90% interval 0.83 to 1.04.
Homologues: Orthologues: chimpanzee ROM1 (99% identical), macaque ROM1 (96% identical), rabbit ROM1 (86% identical), dog ROM1 (85% identical), rat Rom1 (85% identical), pig ROM1 (85% identical), mouse Rom1 (84% identical), guinea pig ROM1 (77% identical), zebrafish rom1b (38% identical), tropical clawed frog rom1 (35% identical), zebrafish rom1a (34% identical). Paralogues in human: PRPH2 (34% identical), TSPAN10 (19% identical), CD37 (16% identical), TSPAN11 (15% identical), TSPAN17 (15% identical), TSPAN14 (14% identical), CD151 (14% identical), CD82 (14% identical), TSPAN5 (14% identical), TSPAN33 (13% identical), TSPAN7 (13% identical), TSPAN9 (13% identical), and 20 more.
Diseases named in the same sentence as ROM1 in open-access papers:
ROM1 is named in the same sentence as 27 diseases in open-access papers, as found by Europe PMC text mining. Sharing a sentence is not in itself a finding about the gene and the disease. The quoted sentences say what the papers report.
retinitis pigmentosa (15 papers, 2016 to 2024). Retinitis pigmentosa (RP) is an inherited retinal dystrophy leading to progressive loss of the photoreceptors and retinal pigment epithelium and resulting in blindness usually after several decades. "Yet, mutations in ROM1 typically cause digenic retinitis pigmentosa in conjunction with mutations in PRPH2, except for a handful of reports of mutations in ROM1 in patients without accompanying PRPH2 mutations." (PMID 37991486, 2023). "For example, certain forms of Retinitis Pigmentosa, a type of blindness, occur in the presence of two mutant variants, one each in the ROM1 and RDS genes, while the occurrence of only one such variant results in a normal phenotype." (PMID 34440333, 2021). "For example, certain forms of Retinitis Pigmentosa (genetic blindness) occur in the presence of two mutant variants, one each in the ROM1 and RDS genes, while the occurrence of only one such variant results in a normal phenotype." (PMID 34440333, 2021). "The ROM1 gene is a member of a photoreceptor-specific gene family and variations in this gene have been associated with retinitis pigmentosa." (PMID 30621171, 2019). "Of note, ROM1 mutations have been associated with retinitis pigmentosa." (PMID 37693346, 2023). "Mutations in PRPH2 (also known as TSPAN22 or RDS) and in ROM1 (also known as TSPAN23), which function together in stabilising the structure of photoreceptor outer segment discs, can cause retinitis pigmentosa, while mutations in TSPAN12 can cause familial exudative vitreo-retinopathy type 5 (EVR5)." (PMID 31073882, 2019). "Four of four SAPs in ROM1 (OMIM:180721) are FN with “Retinitis pigmentosa/macular dystrophy modifier” HGMD annotations." (PMID 27468419, 2016). "An oligogenic disease model has been suggested previously for other ciliopathies, such as the triallelic inheritance of BBS genes in Bardet-Biedl syndrome and digenic inheritance of RDS and ROM1 loci in retinitis pigmentosa." (PMID 26918822, 2016). "Since the first report of digenic variants in retinitis pigmentosa 7 (RP7; OMIM: #608133) in 1994, where heterozygous mutations in two separate loci in ROM1 and RDS gene were described in RP7, the digenic inheritance has been one of the vital mechanisms in RDs." (PMID 36672937, 2023). "Strikingly, eight of the 67 exclusive candidates are associated with retinitis pigmentosa (human orthologues in parentheses): Gnat1 (GNAT1), Rom1a and Rom1b (ROM1), Kfharr-r2 (SAG, ARRESTIN, RP47), Rgra (RGR, RP44), Tbl2 (TBL2), Sec31b (SEC31B) and Glyr1 (GLYR1)." (PMID 34106226, 2021). "Besides, a model of triallelic inheritance of BBS genes was suggested for Bardet-Biedl syndrome, digenic inheritance of unlinked ROM1 and RDS loci was described for retinitis pigmentosa, and digenic trans-heterozygous inheritance of KIF14 and TMEM67 genes—for Meckel Gruber syndrome." (PMID 39180133, 2024).
retinal degeneration (5 papers, 2010 to 2024). Degeneration of the retina. "The Trp182Arg substitution in Rom1 (Rgsc1156) mouse mutants causes progressive retinal degeneration." (PMID 22300709, 2012). "The results of this study provide evidence that a monogenic dominant mutation in Rom1 induces retinal degeneration." (PMID 20300562, 2010). "By contrast, there has been no clear evidence thus far that mutations in retinal outer segment membrane protein 1 (ROM1) alone cause retinal degeneration, although it is well known that only persons who are double heterozygous for ROM1 and PRPH2 develop RP in a digenic inheritance pattern." (PMID 20300562, 2010). "Interestingly, variants in rhodopsin, Pde6a, Pde6b, Prph2 and Rom1 are associated with inherited retinal degeneration in both humans and mice, and their downregulation may underlie the retinal degenerative phenotype observed in Hbs1ltm1a/tm1a mice." (PMID 38966981, 2024). "In conclusion, the evidence is convincing that the Trp182Arg substitution in Rom1Rgsc1156 mutants causes retinal degeneration, suggesting that mutations in the large intradiscal loop of Rom1 may affect the formation of homotetrameric and heterotetrameric core complexes and their stability." (PMID 20300562, 2010). "Various RDS mutations in patients lead to different forms of retinal degeneration which can affect rod- or cone-based vision (or both) and which can affect RDS/ROM-1 complex assembly." (PMID 26406599, 2015). "A study of knockout and transgenic mice showed that retinal degeneration occurs when the combined level of both Rom1 and Prph2 is only about 60% of their combined level in wild-type mice." (PMID 20300562, 2010).
Macular dystrophy (4 papers, 2016 to 2022). Macular dystrophy is a nonspecific term for retinal degeneration, generally confined to the macula, usually presumed of genetic origin. "Interestingly, ROM1 variants cause an ABCA4-like macular dystrophy, raising the possibility that ROM1 dysfunction in the RPE contributes to this phenotype." (PMID 36142331, 2022). "Heterozygous individuals in ABCA4 disease and control cohort harboring variants with MAF<0.005 and CADD score >25, in each macular dystrophy gene CDHR1, CHM, CRX, ELOVL4, PROM1, PRPH2, and ROM1." (PMID 35353811, 2022). "Heterozygous individuals in ABCA4 disease and control cohort harboring rare variants in macular dystrophy genes CDHR1, CHM, CRX, ELOVL4, PROM1, PRPH2, ROM1." (PMID 35353811, 2022). "Although all our patients were diagnosed clinically with STGD, the overlapping of phenotypes between different macular dystrophies and several stages of ABCA4-associated retinopathy could result in a misdiagnosis of STGD with mutations in phenocopying genes, such as PRPH2, ROM1, CRX, or RPGR." (PMID 33841504, 2021).
retinal diseases (4 papers, 2007 to 2022). "Although Rom1−/− mice exhibit much milder phenotype than Prph2 knockouts, and retinal disease attributable to pathogenic mutations in ROM1 alone has yet to be described, ROM1 has been shown to play a significant role in OS biogenesis, especially in the maturation of the OS with PRPH2." (PMID 30630813, 2019). "Together, these findings indicate that Rom-1 might play a yet undefined role in pathophysiology of retinal diseases as a mutation-dependent disease modifier." (PMID 28539581, 2017). "The role of PRPH2 variation in dominant and recessive retinal diseases have been extensively studied, however, much less is known about its oligomerization partner, retinal outer segment membrane protein 1 (ROM1, OMIM #180721)." (PMID 35353811, 2022).
central areolar choroidal dystrophy (3 papers, 2020 to 2024). "In one proband (proband 079830) with a central areolar choroidal dystrophy (CACD) diagnosis, we identified compound heterozygous variants in ROM1—c.339dupG; p.(Leu114Alafs*18) and c.712del; p.(Leu238Cysfs*78)—both of which result in a frameshift." (PMID 38540785, 2024).
retinoblastoma (3 papers, 2021 to 2024). A malignant tumor that originates in the nuclear layer of the retina. "We have successfully identified a few gene signature (CLUL1, CNGB1, ROM1 and RDH12) to predict the risk of invasion in retinoblastoma and therefore, in this study, we investigated the profiles of invasive risk panel between subtypes." (PMID 37777551, 2023). "It has been reported that CLUL1, CNGB1, ROM1, LRRC39, and RDH12 genes in different retinoblastoma subtypes are involved in the progression and development of the disease, which can be useful as biomarkers (M.)." (PMID 34646884, 2021). "Interestingly, the retinoblastoma invasion markers (CLUL1, CNGB1, ROM1 and RDH12) were predominantly higher in subtype 1b, suggesting subtype 1b retinoblastoma prone to be more invasive as compared with other subtypes." (PMID 37777551, 2023).
Blindness (2 papers, 2021 to 2022). Blindness is the condition of lacking visual perception defined as a profound reduction in visual perception. "High-risk PRPH2 and ROM1 mutations causing blindness map to the protein-dimer interface." (PMID 36351012, 2022).
Leber congenital amaurosis (2 papers, 2020 to 2023). Leber congenital amaurosis (LCA) is a retinal dystrophy defined by blindness and responses to electrophysiological stimulation (Ganzfeld electroretinogram (ERG)) below threshold, associated with severe visual impairment within the first year of life. "In rare cases, it is inherited in the autosomal recessive mode or as a digenic form in conjunction with a variant of ROM1, resulting in more severe phenotypes such as Leber congenital amaurosis (LCA; OMIM 608133) and early-onset RP." (PMID 37047703, 2023). "Other diseases, most notablyPRPH2- and ROM1-associated patterndystrophy and RDH12-associated Leber congenital amaurosis(LCA), have been reported to exhibit a similar manifestation although not asconsistent as in ABCA4-associated retinopathy." (PMID 32278709, 2020).
lung carcinoma (2 papers, 2021 to 2024). "Downregulation of ROM1 displayed an association with the poorly prognostic status of lung cancer patients." (PMID 33680068, 2021). "The results indicated that ROM1 was a probably diagnostic biomarker and was represented as an inhibited gene for lung cancer." (PMID 33680068, 2021). "Among lung cancer patients, we further validated the association between ROM1 expression and prognostic status." (PMID 33680068, 2021). "In the Tumor Genome Atlas (TCGA) cohort, reduced ROM1 level was observed in lung cancer tissues, instead of normal tissues." (PMID 33680068, 2021). "Additional results indicated that highly expressed ROM1 exhibited a positive correlation with the overall survival rate, and ROM1 was probably a promising prognostic biomarker of lung cancer." (PMID 33680068, 2021). "The Transwell test showed that knocking out ROM1 significantly promoted lung cancer cell migration and invasion." (PMID 33680068, 2021). "Transwell analysis results indicated that a significantly increased number of migrated and invaded lung cancer cells were demonstrated in ROM1 knockdown group." (PMID 33680068, 2021). "For the study of ROM1 level in lung cancer, we firstly assessed RNA sequencing data in TCGA database." (PMID 33680068, 2021). "In order to confirm TCGA database results, RT-qPCR was executed to detect ROM1 level in tissues of lung cancer and adjacent normal ones." (PMID 33680068, 2021). "Here, our data demonstrated that ROM1 displayed a relation with lung cancer tumorigenesis and development." (PMID 33680068, 2021). "CCK-8 assay deeply demonstrated that ablated ROM1 induced cell proliferation, indicating that ROM1 modulated lung cancer cell proliferation." (PMID 33680068, 2021). "In conclusion, our data reveal that lung cancer possesses reduced ROM1 and is reported to be related to the tumor stage and prognosis, indicating that ROM1 plays importance in lung cancer." (PMID 33680068, 2021). "Our data conclusively demonstrated that ROM1 modulated lung cancer tumorigenesis and development, as a prognosis and treatment biomarker." (PMID 33680068, 2021). "Herein, we studied ROM1 expression and function in lung cancer through multiple bioinformatics analyses and related experimental data." (PMID 33680068, 2021). "Our study firstly assessed ROM1 expression in lung cancer tissues utilizing RNA sequencing data from TCGA database." (PMID 33680068, 2021). "ROM1 was reduced in lung cancer tissues, and its expression level represented a correlation with tumor stages in LUAD and LUSC." (PMID 33680068, 2021). "Collectively, we assumed that ROM1 was a promising inhibitor gene for lung cancer." (PMID 33680068, 2021). "Thus, ROM1 was perhaps involved in lung cancer development by modulating cell proliferation, invasion, and metastasis." (PMID 33680068, 2021). "The clinical feature and biological function of ROM1 in lung cancer are yet elusive." (PMID 33680068, 2021). "ROM1 was knocked down by siRNAs and further evaluated its role in lung cancer." (PMID 33680068, 2021). "Our data indicated that lowly expressed ROM1 was shown in lung cancer cells and its reduction could induce cancer progression." (PMID 33680068, 2021). "Nevertheless, studies towards the role of ROM1 in lung cancer are few." (PMID 33680068, 2021). "Our study collectively indicates that ROM1 is beneficial for lung cancer diagnosis and treatment." (PMID 33680068, 2021). "We also explored how ROM1 influenced lung cancer cells in proliferation, migration and invasion." (PMID 33680068, 2021). "In comparison with that in normal lung cells, ROM1 in lung cancer cells was largely lower." (PMID 33680068, 2021). "Reduced ROM1 level was both shown in lung cancer tissues and cells." (PMID 33680068, 2021). "We found that knocking out ROM1 significantly promoted lung cancer cell proliferation." (PMID 33680068, 2021).
lung carcinoma (continued). "The retinal outer segment membrane protein is abnormally expressed in many cancers, but the mechanism of ROM1 gene in lung cancer is unknown." (PMID 33680068, 2021). "Considering ROM1 expression level, we believed that ROM1 might function as lung cancer inhibitor." (PMID 33680068, 2021). "Additionally, ROM1 level in lung cancer cell lines was measured." (PMID 33680068, 2021).
malaria (1 paper, 2011). Malaria is a serious and sometimes fatal disease caused by a parasite that commonly infects a certain type of mosquito which feeds on humans. "Using the rodent malaria parasite, Plasmodium yoelii, we investigated the specific role of ROM1 during the parasite lifecycle." (PMID 21909259, 2011). "In this study we have characterized the rhomboid protease, ROM1, throughout the lifecycle of the malaria rodent model, Plasmodium yoelii." (PMID 21909259, 2011). "We studied the microneme rhomboid protease, ROM1 in the rodent malaria parasite, Plasmodium yoelii." (PMID 21909259, 2011).
metastatic tumor (1 paper, 2024). "Significant gene upregulation of these tetraspanins (CD53, ROM1, TSPAN3, TSPAN12, TSPAN15, and UPK1B) within immune cells in metastatic tumor suggests their potential involvement in the influence of immune responses." (PMID 38255741, 2024).
pattern macular dystrophy (1 paper, 2019). "ROM1 and PRPH2 pattern macular dystrophies exhibit phenotype overlap, which may be attributable to their shared role in maintenance of the photoreceptor outer segment structure." (PMID 30630813, 2019).
retinal (1 paper, 2014). "Rod outer segment (OS) morphogenesis involves assembly of flattened discs circumscribed by a hairpin-like rim, however, the role of the rim and rim proteins such as retinal degeneration slow (RDS) and its homologue rod OS membrane protein-1 (ROM-1) in this process remains unclear." (PMID 24897172, 2014).
cancer (3 papers, 2021 to 2024). A tumor composed of atypical neoplastic, often pleomorphic cells that invade other tissues. "The findings indicated that the expression of ROM1 was notably elevated in cancers associated with CHOL, KIRC, and THCA." (PMID 38484139, 2024). "Further investigation has been conducted to examine the expression pattern of ROM1 over various types of cancer." (PMID 38484139, 2024). "Furthermore, a prognostic analysis has been done to examine the influence of ROM1 on cancer prognosis." (PMID 38484139, 2024). "ROM1 mRNA has been reported to participate in many cancers' progressions." (PMID 33680068, 2021). "Finally, we find that ROM1 is lowered in IVDD and is linked to various cancer prognoses." (PMID 38484139, 2024).
retinal disorder (2 papers, 2015 to 2021). Any disease or disorder of the retina. "Mutations in ROM1 and the implication in retinal disorders are a matter of discussion and larger pedigrees are necessary to validate the pathogenicity of a variant." (PMID 26103963, 2015).
Tumor (2 papers, 2021 to 2022). "After bioinformatics analysis, the data revealed that ROM1 level was associated with the tumor stage." (PMID 33680068, 2021). "Some related reports indicate that the outer retinal membrane protein 1 (ROM1) functions importantly in the regulation of the biological process of tumor." (PMID 33680068, 2021). "Our results indicated that ROM1 level displayed correlation with the tumor stage in LUAD and LUSC." (PMID 33680068, 2021).
ROM1 also shares sentences with these, for which no sentence is quoted: Bardet-Biedl syndrome (2 papers); adult-onset vitelliform macular dystrophy (1); cataract (1); ciliopathies (1); clear cell renal cell carcinoma (1); dyslipidemia (1); glioma (1); macular degeneration (1); Meckel Gruber syndrome (1); night blindness (1); retinitis punctata albescens (1).